KLF4 (KLF transcription factor 4)
Diseases named in the same sentence as KLF4 in open-access papers (continued):
Sharing a sentence is not in itself a finding about the gene and the disease.
breast cancer (continued). "Hence, the actions of KLF4 are highly dependent upon cell and tissue context, with its specific roles in breast cancer remaining controversial." (PMID 32552913, 2020). "In addition, patients with locally advanced breast cancer with high KLF4 expression have lower pathologic complete remission (pCR) rates after neoadjuvant chemotherapy." (PMID 33266506, 2020). "As in CRC, KLF4 serves as a tumor suppressor in breast cancer and sensitizes breast cancer cells to various forms of treatment, but it can also act as a tumor promoting factor in breast cancer." (PMID 33266506, 2020). "For example, both mRNA and protein levels of KLF4 are elevated during breast cancer progression." (PMID 31245293, 2019). "However, in squamous cell carcinoma, breast cancer, osteosarcoma, and glioma, KLF4 was shown to promote cell growth and cellular dedifferentiation, and inhibit cell apoptosis." (PMID 30658712, 2019). "Recently, PRMT5 has also been shown to methylate a key stemness factor KLF4 in breast cancer." (PMID 31694585, 2019). "Moreover, miR-7, which enjoys more than 60 binding sites on CDR1as, has been demonstrated to inhibit the proliferation of cancer stem-like cells isolated from breast cancer via modulating Klf4." (PMID 31281369, 2019). "Importantly, KLF4 inhibitor Kenpaullone sensitizes breast cancer cells and xenograft tumors to Paclitaxel and improves therapeutic effects." (PMID 30038266, 2018). "We reasoned that combination of chemotherapy and KLF4 inhibitors like Kenpaullone (KEN) might have a synergetic effect on killing breast cancer cells." (PMID 30038266, 2018). "In vitro, the combination has downregulated KLF4, which acts as an oncogene in breast cancer." (PMID 29899271, 2018). "KLF4 overexpression induced a switch from a mesenchymal to epithelial state in breast cancer cells." (PMID 29747682, 2018). "The researchers have also reported that the exposure of breast cancer cells to hypoxia induces zinc finger protein 217 (ZNF217)-dependent inhibition of m6A methylation of mRNAs encoding NANOG and Kruppel-like factor 4 (KLF4), which is another pluripotency factor that mediates BCSC speciation." (PMID 29587823, 2018). "KLF4 is thought to act both as a tumor suppressor and as an oncogene in breast cancer." (PMID 29899271, 2018). "However, in squamous cell carcinoma, breast cancer and osteosarcoma, KLF4 was shown to promote cell growth, cellular dedifferentiation and inhibit cell apoptosis." (PMID 30176890, 2018). "KLF4 is known to activate hTERT, which is highly activated in breast cancer." (PMID 29899271, 2018). "Furthermore, KLF4 mediates resistance to therapy (i.e. lapatinib) and is required for the maintenance of breast cancer stem cells and for migration and invasion." (PMID 28412746, 2017). "Here, we aimed to elucidate whether KLF4α is expressed in breast cancer cells and, if so, whether increased KLF4α levels might explain some of the complexity of KLF4's role in breast tumorigenesis." (PMID 27323810, 2016). "It is well established that KLF4 has ambiguous roles in human breast cancer." (PMID 27323810, 2016). "The role of KLF4 in breast cancer remains less clear and contradictory data exist." (PMID 27323810, 2016). "Unresolved data on the role of KLF4 during breast carcinogenesis, as well as the identification of KLF4α, a KLF4 isoform, as a tumor-promoting gene in pancreatic cancer, prompted us to study KLF4α expression in breast cancer cells." (PMID 27323810, 2016). "The role of KLF4 in breast cancer remains unclear and nothing is known yet about the expression and function of the isoform KLF4α." (PMID 27323810, 2016). "For SNP rs10759243 in the KLF4 gene, the genotype “C/A” increased clinic stage (UICC) III and IV breast cancer risk by1.85-fold (OR = 1.85; 95% CI, 1.14-3.00; p = 0.037) in the codominant model and “C/A-A/A” genotype in the dominant model (OR = 1.79; 95% CI, 1.12-2.85; p = 0.012)." (PMID 27863437, 2016).
breast cancer (continued). "The general discovery of KLF4 variants and our data on KLF4α as an antagonist of KLF4(FL) in breast cancer might shed new light on the role of KLF4 during breast tumorigenesis." (PMID 27323810, 2016). "KLF4 mRNA and protein expression is found to be increased in skin and breast cancer." (PMID 27992436, 2016). "KLF4 has been reported to act as both an oncogene and a tumor suppressor in breast cancer." (PMID 27863437, 2016). "Thus, we propose KLF4α as a novel, so far neglected oncogenic factor, which clarifies the role of KLF4 in breast cancer." (PMID 27323810, 2016). "KLF4 significantly decreases lung and liver metastases in a murine model of mammary cancer." (PMID 26823670, 2016). "We provide evidence that KLF4α has tumor-promoting functions and that its expression may play a significant role in KLF4's complex functions in breast cancer." (PMID 27323810, 2016). "Next, we wanted to quantitatively study RNA levels of the two KLF4 variants in a panel of breast cancer cell lines (MCF7, T47D, MDA-MB-175, and MDA-MB-231), the normal human breast cell line (MCF10A), and also in samples from patients with ductal carcinoma." (PMID 27323810, 2016). "In breast cancer and squamous cell carcinoma, KLF4 was found to be an oncogenic protein." (PMID 27105535, 2016). "However, in other types of primary tumors, such as breast cancer, the expression of KLF4 is upregulated." (PMID 27022622, 2016). "KLF4 inhibits breast cancer cell proliferation, migration and invasion." (PMID 26110566, 2015). "KLF4 is associated with cancer stem cell (CSC) phenotype and it up-regulation might suggest an involvement of CSCs in brain metastasis of breast cancers." (PMID 25893380, 2015). "Furthermore, induction of KLF4 in response to oestrogen receptor stimulation suggests a role of KLF4 in facilitating cell growth through mediating oncogenic signalling in mammary gland epithelial or breast cancer cell." (PMID 26420673, 2015). "KLF4 has been reported to be an oncogene mainly in breast cancer." (PMID 26517087, 2015). "This includes miR-29c, which has been shown to regulate Klf4 expression in breast cancer cells." (PMID 25928148, 2015). "Notably, Klf4 showed continuous increase according to paclitaxel administration in breast cancer patients." (PMID 26462028, 2015). "Consequently, overexpression of KLF4 in the metastatic MDA-MB-231 breast cancer cell line dramatically increased CDH1 and KRT18 expression, indicating the restoration of an epithelial phenotype and loss of metastasis." (PMID 24429391, 2014). "Furthermore, downregulation of KLF4 inhibited breast cancer cell migration and invasion through Notch (NOTCH1)-mediated activity." (PMID 24429391, 2014). "In breast cancer, KLF4 can function both as an oncogene and a tumor suppressor." (PMID 25137052, 2014). "Furthermore, KLF4 is necessary in the adaptation of metastatic breast cancer cells in the brain niche." (PMID 24429391, 2014). "KLF4 can have a dual effect either as an oncogene or a tumor suppressor in breast cancer cells." (PMID 25137052, 2014). "In addition, reduced Klf4 expression correlates with shorter disease-free survival of subsets of breast cancer patients." (PMID 23451207, 2013). "Moreover, in the TRANSBIG breast cancer database, low Klf4 expression levels correlated with shorter relapse-free survival of ER+ breast cancer patients." (PMID 23451207, 2013). "We next assessed whether decreased expression of Klf4 correlated with the ability of breast cancer to progress and metastasize in patients." (PMID 23451207, 2013).
breast cancer (continued). "Moreover, we find that high Klf4 expression correlates with increased disease-free survival in patients, for example in the Uppsala breast cancer database and in the TRANSBIG breast cancer database." (PMID 23451207, 2013). "As a consequence, tumor growth and tumor weight were significantly increased upon activation of Klf4, yet decreased luciferase levels were observed in organs that are known targets of metastasizing breast cancer cells, such as lung and liver (metastatic index)." (PMID 23451207, 2013). "It was reported that KLF4 is required for maintenance of breast cancer stem cells." (PMID 23418515, 2013). "However, the cytoplasmic location of KLF4 expression is a poor prognostic factor in early-stage breast cancer." (PMID 23861801, 2013). "Several transcription factors, e.g. Gata3 and Klf4, have been identified that could induce E-cadherin expression through binding to E-cadherin promoter in human breast cancer cells." (PMID 23284647, 2012). "Previous studies suggested that KLF4 regulates E-cadherin gene expression by binding a GC-rich/E-box region in its promoter, and further demonstrated that enhanced levels of KLF4 resulted in the restoration of E-cadherin expression in breast cancer cells." (PMID 22937066, 2012). "Among the KLFs, KLF4 is highly expressed in human breast cancers and plays an oncogenic role." (PMID 21978458, 2011). "As in human breast cancer, KLF4 plays an oncogenic role in canine mammary carcinoma." (PMID 21978458, 2011). "This evidence suggests that the altered expression levels of CARD10, KLF4, Acly, Atp1b1, and Spint2 may be contributing factors in the higher mortality rates of AA breast cancer patients." (PMID 17472751, 2007). "Results from this study indicates that altered expression of the genes Atp1b1, CARD 10, KLF4, Spint2, and Acly may play a role in the aggressive phenotype seen in breast cancer in African American women." (PMID 17472751, 2007). "However, in breast cancer, KLF4 exhibits both tumor‐suppressive and oncogenic activities." (PMID 41532367, 2026). "Importantly, a reduction in KLF4 results in reduced metastatic potential of breast cancer cells." (PMID 40552304, 2025). "Interestingly, Klf4 expression was regulated by miR-34a, a miRNA that progressively increases with the development of dietary obesity and is related to cervical and breast cancer." (PMID 38668382, 2024). "However, the mechansims of ATXN3 up-regulation in breast cancer, how KLF4 promotes breast cancer, and whether aberrant deubiquitination of KLF4 by ataxin-3 is involved in the pathophysiology of MJD, remain to be explored." (PMID 38497605, 2024). "LINC00115 promotes breast cancer metastasis by regulating the expression levels of miR-7 and KLF4; LINC00115 is significantly upregulated in HPV-negative cervical cancer cells and can promote the proliferation, migration, and migration of these cells; however, its role in RB remains unknown." (PMID 35184643, 2022). "KLF4 has been shown to interact directly with Oct4 and Sox2 which are critical for somatic cell reprogramming, while in breast cancer, KLF4 may have a potent oncogenic role in tumorigenesis by maintaining stem cell-like features and by promoting cell migration and invasion." (PMID 35158755, 2022). "In addition, DIM could effectively increase the sensitivity of MCF-7 and T47D breast cancer cells to PTX by downregulating KLF4 methylation through inhibiting DNMT1." (PMID 34150611, 2021). "We further investigated whether DIM regulates the methylation level of KLF4 promoter in breast cancer cells, and the results showed that compared with normal cells, the methylation level of CpG sites (−148 bp) in the KLF4 promoter was decreased in breast cancer MCF-7 cells after treatment with DIM." (PMID 34150611, 2021). "Moreover, we also detected whether LINC00115 can inhibit the expression of KLF4, which is a confirmed target of miR‐7 in breast cancer." (PMID 32175684, 2020).
breast cancer (continued). "Moreover, KLF4 and EGFR protein expression are generally mutually exclusive in the breast cancer cell lines we examined, suggesting that a threshold level of endogenous KLF4 may suppress the expression of EGFR in breast cancer cells." (PMID 32552913, 2020). "In addition, KLF4 maintains the stemness in osteosarcoma, breast cancer, and prostate cancer." (PMID 33052880, 2020). "Moreover, through the regulation of E-cadherin or Snail, KLF4 inhibits EMT in breast cancer cells." (PMID 33240028, 2020). "Klf4 with Oct4 and Sox2 induces the expression of Lefty1 and Nanog, KLF4 is also a prognostic predictor of colon cancer and head neck squamous cell carcinoma, and is also detected in leukemia, myeloma, testis cancer, early stage breast cancer, nasopharyngeal cancer, and oral cancer." (PMID 32493501, 2020). "Thus the overall picture of KLF4 involvement in breast cancer is even more complicated than in CRC." (PMID 33266506, 2020). "However, KLF4 is highly expressed in more than 70% of breast cancers and functions as an oncogene." (PMID 29899271, 2018). "Because KLF4 is an essential gene for breast cancer stem cell maintenance and it's decrease leads to decreased proportion of stem/progenitor cells, B6H12 treatment may reduce the number of bCSC by down-regulation of KLF4, leading to the observed inhibition of asymmetric cell division." (PMID 26840086, 2016). "Also, it will be interesting to see how KLF4α/KLF4(FL) imbalance affects the cancer stem cell-like population, which plays an important role in tumor development and emergence of therapy-resistant clones in breast cancer." (PMID 27323810, 2016). "The SNPs rs10759243 in the KLF4 gene (OR = 1.284, 95% CI, 1.061 – 1.552, p = 0.010) and rs704010 in the ZMIZ1 gene (OR = 1.237, 95% CI, 1.010 – 1.515, p = 0.040) were associated with the risk of clinical stage (UICC) I and II breast cancer compared with normal controls." (PMID 27863437, 2016). "However, recent evidence suggests that KLF4 might also act as an oncogene in breast cancer, head and neck cancer (HNSCC), and pancreatic cancer." (PMID 26823670, 2016). "Therefore, we speculated that NFI-C also regulates the balance between KLF4 and E-cadherin in breast cancer cells, which is important for MET." (PMID 25879941, 2015). "For example, miR-10a-5p as a vital modulator, could suppress the growth of chronic myeloid leukemia CD34+ cells, and miR-10b-5p targets the potent inflammatory mediator KLF4 (Kruppel-like factor 4) and has important roles in tumor invasion and the initiation of metastasis in breast cancer." (PMID 24223210, 2013). "Notably, Klf4 is a major repressor of EMT: its expression prevents EMT and maintains an epithelial morphology of mammary epithelial cells and of breast cancer cells, while its ablation results in a loss of epithelial morphology and in a partial induction and acceleration of EMT." (PMID 23451207, 2013). "In breast cancer, PRMT5 modulates the sensitivity of breast cancer cells to doxorubicin by regulating OCT4/A, KLF4 and C-MYC." (PMID 41513606, 2026). "Kenpaullone inhibits KLF4 by suppressing CDK1/cyclin B and GSK-3β, reducing proliferation and migration of breast cancer cells in canine mammary cancer and inducing cancer cell death, although its effects in humans require further investigation." (PMID 39995670, 2025). "In breast cancer, KLF4 contributes to the maintenance of high glycolytic metabolism through the transcriptional activation of the PFKP gene, which further supports breast cancer progression." (PMID 40616161, 2025). "TPA stimulates breast cancer cell motility by modulating the expression and activity of S100A14 in a KLF4-dependent manner." (PMID 40182023, 2025). "The importance of DDX proteins in regulating KLF4 splicing was also shown by its physical interactions with DDX17 in hepatocellular carcinoma and with DDX3X in breast cancer cell cycle progression." (PMID 40552304, 2025).
breast cancer (continued). "In breast cancer, PRMT5 promotes tumor growth by methylating key substrates: it stabilizes KLF4 by inhibiting its ubiquitylation, leading to Bax downregulation and oncogene upregulation, and it methylates PDCD4, abolishing its tumor-suppressive function." (PMID 41204384, 2025). "In breast cancer, PRMT5 regulates OCT4/A, KLF4, FOXP1, and c-Myc expression to promote CSC proliferation, self-renewal, and resistance." (PMID 41204384, 2025). "We found that primary lung pericytes expressed the stem/plasticity factor Klf4 and increased proliferation in response to TCM from the metastatic breast cancer cell line, 4T1." (PMID 39609469, 2024). "For example, KLF4 activates the transcription of the PFKP gene by directly binding to the PFKP promoter, playing a critical role in cell proliferation in breast cancer cells." (PMID 38982480, 2024). "In breast cancer, DDX3X has been found to inhibit the expression of the transcription factor Kruppel-like factor 4 (KLF4)." (PMID 38539466, 2024). "Hypoxia induces breast cancer stem cell (BCSC) specification by inducing the expression and/or activity of the pluripotency factors KLF4, NANOG, OCT4, and SOX2." (PMID 37768037, 2023). "HDAC2 and 3 are recruited by Kruppel-like factor 4 (KLF-4) at the vascular endothelial growth factor (VEGF) promoter to participate in transcriptional repression of VEGF, which has been first reported in breast cancer." (PMID 37533111, 2023). "A heat map generated using data from TCGA (BRCA- breast cancers) showed that OCT4 and MYC were overexpressed in basal-like breast cancers while SOX2 and KLF4 were down regulated in this subtype." (PMID 37515162, 2023). "Several transcriptional activators have been identified to regulate hTERT expression in breast cancer cells, including c-MYC, STAT3, NF-κB, ETS2, ERα, Sp1, KLF4, and ZEB1/YAP, among others." (PMID 37612721, 2023). "ChIP-seq analysis reveals significant overlap between PML-, ER-, and Myc-bound promoters, suggesting their coordinated regulation of target gene expression, including genes involved in breast cancer stem cells (BCSCs), such as JAG1, KLF4, YAP1, SNAI1, and MYC." (PMID 37720048, 2023). "KLF4 is an embryonic stem cell (ESC) marker and a transcription factor (TF) that is expressed at high levels by most breast cancer cell types." (PMID 37250812, 2023). "Mechanistically, B6H12 treatment facilitates the expression of exosomal microRNA-7 in breast cancer stem cells, which targets EGFR and KLF4 mRNAs, leading to decreased EGFR, KLF4, and EGF-induced EGFR tyrosine phosphorylation." (PMID 36233088, 2022). "Although a study on breast cancer reported that NFRSF17 can act as a co-receptor of ALDH1A1, KLF4 and NANOG, mediating their tumour-promoting effects in breast cancer." (PMID 36203424, 2022). "In breast cancer, eight winning TFs (ZBTB16, KLF2, KLF4, NR2F1, EGR1, FOSB, EPAS1, and GPRASP1) can form a coregulatory network, and three other winning TFs (MYBL2, FOXM1, and TAL1) can form another coregulatory network." (PMID 36101460, 2022). "In 2016, research showed that ZNF217 inhibited the m6A methylation of KLF4 and NANOG mRNA, which was catalyzed by METTL3 and resulted in elevated KLF4 and NANOG protein levels, which in turn promoted the progression of breast cancer." (PMID 35945641, 2022). "The lentivirus carrying KLF4 and DNMT1 gene or shRNA targeting DNMT1 were used to overexpress KLF4 or knockdown DNMT1 in MCF-7 and T47D breast cancer cells and the role of KLF4 and DNMT1 in regulation of PTX sensitivity was investigated." (PMID 34150611, 2021).